NRP2 (neuropilin 2)
Diseases named in the same sentence as NRP2 in open-access papers (continued):
Sharing a sentence is not in itself a finding about the gene and the disease.
breast carcinoma (continued). "In contrast, miR-486 inhibits cell proliferation and invasion through repressing GAB2, PIK3R1, Snail, neuropilin-2, CDK4, or PIM-1 in non-small-cell lung cancer, colorectal cancer, prostate cancer, hepatocellular carcinoma, and breast cancer cells." (PMID 32155804, 2020). "For example, in breast cancer, VEGFR-bound NRP2 interacts with the α6β1 integrin, thus inducing the α6β1 integrin to bind with the ligand laminin, be involved in the formation of focal adhesions, and lead to the formation of focal adhesion kinases (FAKs)." (PMID 30871059, 2019). "We propose that HRH1, NRP2, and STX1A can be used as prognostic biomarkers and therapeutic targets for basal and HER2-enriched breast cancer subtypes." (PMID 26673618, 2016). "Studies in breast cancer cells showed that NRP1 and NRP2 have a similar affinity for TGFBR1, whereas NRP2 has a higher affinity for TGFBR2 that TGFBR1." (PMID 26923176, 2016). "Indeed, our finding that NRP2 Ab treatment of tumours reduced tumour volume but it did not inhibit tumour angiogenesis significantly suggests that anti-NRP2 therapy could be highly effective when used in conjunction with anti-angiogenesis therapies for the clinical management of breast cancer." (PMID 23436775, 2013). "However, NRP2 expression was found in osteosarcomas, melanomas, lung cancers, brain tumors colon cancers, pancreatic cancers, breast cancers, myeloid leukemias, salivary adenoid cystic carcinomas (SACCs), infantile hemangiomas, ovarian neoplasms and bladder cancers." (PMID 24212788, 2011). "In another study, Kigel and colleagues transfected breast cancer cells expressing NRP1 and-or NRP2 with each semaphorin to analyze their role in tumor progression in xenograft experiments." (PMID 24212788, 2011). "Nrp2 expression is significantly correlated with VEGF-C expression, cytoplasmic CXCR4 expression, and lymph node metastasis in breast cancer." (PMID 19580679, 2009). "In this study, we examined the relationship of Nrp2 to lymph node metastasis, VEGF-C expression, and CXCR4 expression in human breast cancer tissues, and further investigated the potential value or relevance of Nrp2 for predicting disease outcome." (PMID 19580679, 2009). "Effects of neutralizing anti-Nrp2 antibody on CXCR4 expression and chemotaxis were assessed in MDA-MB-231 breast cancer cells." (PMID 19580679, 2009). "We then showed that an antibody against Nrp2 reduces cytoplasmic CXCR4 expression and inhibited CXCL12-induced chemotaxis in MDA-MB-231 breast cancer cells, which were previously shown to express endogenous Nrp2." (PMID 19580679, 2009). "However, the role of Nrp2 in human breast cancer is largely unknown." (PMID 19580679, 2009). "In the present study, treatment of the MDA-MB-231 breast cancer cell line, which express Nrp2, endogenous VEGF-C, and cytoplasmic or nuclear CXCR4, with anti-Nrp2 antibody significantly inhibited cytoplasmic CXCR4 protein expression." (PMID 19580679, 2009). "In breast cancer, a fully humanized, high-affinity monoclonal antibody (aNRP2-10) has recently been developed to specifically block the interaction between VEGF and its co-receptor neuropilin-2 (NRP2)." (PMID 41373619, 2025). "NRP2 protein levels were examined by immunostaining and comprising 10 cases of paired non-tumor and primary breast cancer tissues." (PMID 28418877, 2017). "The results showed that higher levels NRP2 in membrane and cytoplasimic was detected in all primary breast cancer tissues than in non-tumor." (PMID 28418877, 2017). "MDAMB231 breast cancer-cell line expressed NRP2 whereas no NRP2 staining was found on Burkitt lymphoma cells lines (Raji, Jijoye)." (PMID 21747928, 2011).
breast carcinoma (continued). "Nrp2 is also known to function as a receptor for VEGF-C, which is a well-known lymphangiogenic factor and plays an important role in lymph node metastasis of various human cancers, including breast cancer." (PMID 19580679, 2009). "Neuropilin-2 (Nrp2) is a receptor for vascular endothelial growth factor-C (VEGF-C), which is a well-known lymphangiogenic factor and plays an important role in lymph node metastasis of various human cancers, including breast cancer." (PMID 19580679, 2009). "Moreover, immunohistochemical staining showed that NRP2 is expressed at the membrane of human colon carcinoma and breast carcinoma while it is not expressed in non malignant tissues." (PMID 21747928, 2011). "The relationship between Nrp2 expression and lymph node metastasis, VEGF-C expression, CXCR4 expression, and other established clinicopathological variables (these data were cited in our previous papers), including prognosis, was analyzed in human breast cancer." (PMID 19580679, 2009). "Depending on the tumoral tissue, NRP-2 can be overexpressed in CRC and breast cancer or can be completely absent in cancers such as prostate cancer and B cell lymphoma." (PMID 35052853, 2022). "Our analysis showed that PLXNA3, B2, and C1 were significantly upregulated, and NRP1, NRP2, PLXNA1, A2, A4 were significantly downregulated, while the rest of the members (PLXNB1, B3 and D1) were not differentially expressed in breast cancer tumors." (PMID 32640719, 2020). "In vitro, exogenous Sema3f inhibits cell attachment and spreading in the breast cancer cell line MCF7, a line that expresses Nrp1 but not Nrp2; this inhibition is blocked by the addition of anti-Nrp1 functional blocking antibody." (PMID 22783168, 2012).
prostate carcinoma (27 papers, 2011 to 2025). A carcinoma that arises from epithelial cells of the prostate gland. "Lastly, Nrp2-mediated regulation of the androgen receptor (AR), a ligand-dependent nuclear transcription factor, is implicated in prostate cancer progression and resistance to therapy." (PMID 38592275, 2024). "As concerning NRP2, the soluble splice variant s9Nrp2 has been found to interfere with the VEGF-C/NRP2 signaling axis in prostate cancer." (PMID 31027288, 2019). "CNS tumors (e.g. neuroblastoma) frequently express NRP-2, and NRP-2 expression is also elevated in high-grade prostate cancers with PTEN loss, a frequent event in glioblastoma." (PMID 24142150, 2014). "Understanding the role of neuropilin 2 (NRP2) in prostate cancer cells as well as in the bone microenvironment is pivotal in the development of an effective targeted therapy for the treatment of prostate cancer bone metastasis." (PMID 33990538, 2021). "Our results revealed NRP2 negatively regulates osteoclast differentiation and function in the presence of prostate cancer cells that promotes mixed bone lesions." (PMID 33990538, 2021). "This study also provided evidence that bevacizumab or VEGFR-targeted therapy in prostate cancer is more efficacious if it is combined with targeted inhibition of the NRP2 effectors P-Rex1 and Rac1." (PMID 30678134, 2019). "A soluble splice variant of NRP2, s9NRP2, scavenges VEGF-C and inhibits VEGF-C/NRP2 signaling in prostate cancer." (PMID 30717262, 2019). "Expression of COUP transcription factor II (COUP-TFII) correlates with disease recurrence and progression in prostate cancer and it can directly stimulate the transcription of NRP2." (PMID 30678134, 2019). "A similar expression pattern has been observed in prostate cancer where NRP2 expression correlates with Gleason grade and it is also enriched in prostate CSCs." (PMID 30678134, 2019). "We determined the mRNA and protein expression of these two molecules following depletion of NRP2 in prostate cancer cell line PC3." (PMID 27026195, 2016). "We have previously reported that syndecan-1 (CD138) up-regulates miR-331-3p expression by directly targeting neuropilin 2 (NRP2) and nucleus accumbens-associated protein 1 (NACC1) to mediate the EMT in prostate cancer cells." (PMID 27548144, 2016). "Moreover, the blockade of the binding of VEGF to NRP2 using a mouse-specific anti-NRP2 monoclonal antibody led to necrosis and tumour regression in mouse prostate cancer models." (PMID 39941741, 2025). "Moreover, others have shown that specific Nrp2 abrogation in osteoclasts decreases the in vivo capacity of prostate cancer cells to metastasize to the bone." (PMID 37600714, 2023). "Since PCa promotes predominantly osteoblastic bone formation, an approach that enhances osteolytic activity, e.g. targeting NRP2, may interfere with prostate cancer growth in bone." (PMID 33990538, 2021). "We observed a significant upregulation of NRP2 in prostate cancer cells metastasized to bone." (PMID 33990538, 2021). "NRP2 transcription can also be stimulated by the COUPTF2 transcription factor in prostate cancer." (PMID 30871059, 2019). "PTEN loss induces NRP2 transcription in prostate cancer by a mechanism that involves the Jun N-terminal kinase (JNK)/c-jun pathway, providing a direct link between the loss of a tumor suppressor and induction of NRP2 transcription." (PMID 30678134, 2019). "For example, the antioxidant enzyme Peroxiredoxin II regulates VEGF signaling in liver CSCs by upregulating BMI1 and Sox2 through a VEGFR-2/STAT3 pathway, while VEGF and VEGF receptor neuropilin-2 signaling involved a BMI1-mediated mechanism in aggressive prostate cancer." (PMID 30002682, 2018). "NRP2 is necessary for BMI-1 expression, consistent with our previous finding in prostate cancer." (PMID 23436775, 2013). "For example, a soluble form of NRP2 has been shown to scavenge VEGF-C and inhibit pathological NRP2/VEGF-C signalling in a prostate cancer cell line." (PMID 32708258, 2020).
prostate carcinoma (continued). "Because OPN is also associated with bone matrix formation, it would be highly interesting to analyze if the connection between NRP2 and OPN is also true for cancer entities like breast and prostate cancer, where bone metastases remain a big challenge." (PMID 32038994, 2019). "In prostate cancer, phosphatase and tension homolog (PTEN) is responsible for the induction of NRP2 through the JUN N-terminal kinase (JNK)-JUN pathway." (PMID 30871059, 2019). "We have previously reported that syndecan-1 (CD138) up-regulates miR-331-3p expression by directly targeting neuropilin 2 (NRP2) and NACC1 to mediate the EMT in prostate cancer cells." (PMID 30248959, 2018). "Taken together, these data suggest that Plexin B1 and coreceptors, NRP1 and NRP2, mediate SEMA3C signaling in prostate cancer cells." (PMID 29348142, 2018). "Here we showed that in prostate cancer cells, FAC1 was directly recruited to the WDFY1 promoter and inhibited its transcription in the presence of NRP2." (PMID 27026195, 2016). "Gene ontology analysis of differentially expressed genes revealed that lack of Sost in the bone microenvironment up-regulated several genes associated with the GO term “chemotaxis” including MET, PDGFA, FER, NRP2, and EZR in prostate cancer." (PMID 27600237, 2015). "Moreover, NRP2, in concert with VEGF, regulates IGF-1R expression and signaling in prostate cancer cells." (PMID 37600714, 2023). "In prostate cancer, NRP2, mediates bevacizumab resistance via a VEGF/NRP2/PREX1/RAC1 pathway." (PMID 35875157, 2022). "Moreover, Nrp2 deletion in osteoclasts (or its precursors) is accompanied by elevated osteoclastogenesis when cultured in presence of M-CSF and RANKL or when incubated with conditioned medium of metastatic prostate cancer cells." (PMID 37600714, 2023).
lung carcinoma (23 papers, 2011 to 2025). "NRP2 consists of several splice variants; the most abundant of these, NRP2a and NRP2b, are reported to have different biological functions in lung cancer progression." (PMID 33918816, 2021). "Determining the clinical relevance of these findings will enhance the prospects of miR-200 and NRP2 as potential therapeutic targets in the treatment of lung cancer." (PMID 38766528, 2024). "In lung cancer, Nrp2 expression is correlated with advanced disease stage at diagnosis, epithelial-to-mesenchymal transition (EMT), metastasis, decreased survival, and drug resistance." (PMID 38592275, 2024). "Nrp2 is upregulated in pMacs adjacent to lung cancer margins, with reduced expression in pMacs in distant normal lung tissue." (PMID 38592275, 2024). "Here, TGFβ upregulates Nrp2 and preferentially Nrp2b, which enhanced cellular migration, invasion into Matrigel, and tumorsphere formation in lung cancer cells, as well as promoted metastasis in lung cancer xenograft mouse models." (PMID 38592275, 2024). "Within patients with lung cancer and mouse models, Nrp2 isoforms can have markedly different effects on tumor biology." (PMID 38592275, 2024). "TGFβ is an integral driver of EMT, promoting lung cancer metastasis, and Nrp2 is correlated with EMT phenotypes." (PMID 38592275, 2024). "Knockdown of either total Nrp2 or Nrp2b in lung cancer models significantly inhibited tumor formation, whereas Nrp2a knockdown had only a modest effect." (PMID 38592275, 2024). "miR-200 also reduces CAF interactions with macrophages and endothelial cells, proposing miR-200 and NRP2 as targets for lung cancer treatment and prognosis." (PMID 38766528, 2024). "Both mRNA and protein levels of VEGF-D and PTN decreased with miR-200 overexpression and Nrp2 knockdown, and reportedly promoted the migration and metastasis of lung cancer cells." (PMID 38766528, 2024). "As the endothelial codepletion of NRP1 and NRP2 was found to effectively impair primary lung carcinoma growth and angiogenesis, we proceeded to assess the efficacy of their codepletion in other paradigms of cancer." (PMID 36970722, 2022). "Mesenchymal-epithelial transition (MET) is known to be an essential process involved in tumour cell invasion and metastasis, and NRP2 contributes significantly to TGF-β1-induced EMT in lung cancer." (PMID 36172369, 2022). "It is also feasible that NRP2 isoform levels vary between bladder and lung tissue or that NRP2 isoforms are differentially involved in bladder cancer vs. lung cancer." (PMID 33918816, 2021). "Among them, we focused on Nrp2 and Vegfa, whose role in maintaining stemness and proliferation in lung cancer stem cells we recently demonstrated." (PMID 30483126, 2018). "Neuropilins (NRP1 and NRP2) are overexpressed in several cancers, and their expressions correlate with increased invasion and poor prognostic in lung cancer." (PMID 28804523, 2017). "In TGFβ-induced EMT in lung cancer cells, we found increased expression of Neuropilin-2 (NRP2), the receptor for class 3 semaphorins, ligands providing guidance to and control of cell movement." (PMID 28672805, 2017). "Induction of neuropilin-2 levels in lung cancer cells contributes to EMT, invasiveness and metastasis; furthermore, neuropilin-2 is highly expressed in HCCs with mesenchymal features and also contributes to the invasiveness of these tumor cells." (PMID 27367735, 2016). "Comparison of neuropilin-1 (NRP-1) and neuropilin-2 (NRP-2) expression on alveolar macrophages in lung cancer adjacent to the cancer margin, lung inflammation and lung tissue remote to the cancer nest (physiologically normal lung)." (PMID 26900851, 2016). "As these pathways exhibit compensatory activation upon cabozantinib treatment in resistant cells, we investigated whether VEGFC/KDR/NRP2 knockdown elicited a decrease in FGF/YAP/TAZ/AXL expression in resistant lung cancer cells." (PMID 40843133, 2025). "Little is known about the role of Nrp2 in TAMs during lung cancer." (PMID 38592275, 2024).
lung carcinoma (continued). "Nrp2 isoforms in lung cancer differentially effect MET signaling and recruitment of GIPC1 and PTEN." (PMID 38592275, 2024). "As TAMs are highly immunosuppressive, this suggests that Nrp2 may be involved in the ongoing immune escape of lung cancer." (PMID 38592275, 2024). "NRP-1 and NRP-2 expression increased in AMs under conditions of lung inflammation and lung cancer." (PMID 26900851, 2016). "Furthermore, NRP2 isoforms may have distinct turnover rates as indicated in lung cancer cell lines where the half-life of NRP2b was approximately twice as long as that for NRP2a." (PMID 33918816, 2021). "Here, we showed that miR-200 inhibited CAF activation by targeting NRP2/VEGFR signaling, decreasing the aggressiveness of lung cancer cells, preventing M2 polarization of macrophages, and suppressing the angiogenic sprouting of vascular endothelial cells." (PMID 38766528, 2024). "Among the commonly deregulated genes, we found a significant up-regulation of the Rac Family Small GTPase 1 (RAC1) gene and neuropilin 2 (NRP2), which are involved in tumor migration and invasion in different tumors including lung cancer." (PMID 35884472, 2022). "The tLyp-1 peptide is able to bind to receptors such as neuropilin-1 (NRP1) and neuropilin-2 (NRP2), which are overexpressed on the surface of lung cancer cells." (PMID 35765040, 2022). "In contrast, the level of SEMA3F (semaphorin 3F), a secreted semaphorin with potent antitumor activity that binds NRP2, was decreased in a ZEB1-induced EMT lung cancer model." (PMID 28672805, 2017). "In this study, 95.8% of DC-SIGN+ AMs co-expressed NRP-1 and 94.9% for NRP-2, and there was a correlation between NRP+ AMs and DC-SIGN+ AMs adjacent to lung cancer." (PMID 26900851, 2016). "GLI1, expressed by 76% of lung cancers, can be noncanonically activated by Nrp2/VEGF-mediated MAPK/ERK signaling, and silencing GLI1 attenuates cancer cell stemness and proliferation, and increases their susceptibility to apoptosis." (PMID 38592275, 2024). "Also Nrp2 is involved in EMT and has been reported as up-regulated both in hepatocellular carcinoma and in lung cancer cells after EMT induction by TGF-β1." (PMID 30483126, 2018). "For example, by crossing NRP2-floxed (NRP2flfl) mice with mice expressing a tamoxifen-inducible Pdgfb-iCreERT2 promoter, we previously showed that endothelial NRP2 (NRP2EC) promotes pathologic angiogenesis to support the progression of primary tumors in a lung-carcinoma model." (PMID 36970722, 2022). "Therefore, NRP2 is not involved in angiogenesis in CRC or lung cancer, nor does it promote HUVEC migration." (PMID 32983407, 2020). "Furthermore, NRP2 promotes cell migration in the presence of conditioned medium from pancreatic cancer cells but not from colorectal or lung cancer cells." (PMID 32983407, 2020). "Furthermore, the NRP2 can promotes tumourigenicity and metastasis in oesophageal squamous cell carcinoma through ERK–MAPK–ETV4–MMP–E-cadherin deregulation and it is uniquely support TGF-β-mediated progression in lung cancer." (PMID 28418877, 2017). "NRP-1 and NRP-2 were expressed in AMs in lung cancer patients both with and without smoking habits." (PMID 26900851, 2016). "NRP-1 and NRP-2 expression was also observed in some lung cancer cells (data not provided)." (PMID 26900851, 2016). "NRP2 was also expressed in all renal cancer cell lines tested (HEK 293, Caki, R3III and A498), in two of four pancreatic cancer cell lines (Bes-PAC03 and Bes-PAC04, derived from patient's ascitic fluid in our institute), in NCIH441 lung cancer cell line and in 5637 bladder cancer cell line." (PMID 21747928, 2011). "Interestingly, a role of NRP2 in canonical TGF-β signaling could also not be confirmed in lung cancer cells, however, this study showed that NRP2 affected ERK signaling supposedly via non-canonical TGF-β signaling activity." (PMID 26573807, 2015).